CDX2 (caudal type homeobox 2)
Diseases named in the same sentence as CDX2 in open-access papers (continued):
Sharing a sentence is not in itself a finding about the gene and the disease.
colon carcinoma (continued). "Their finding demonstrated that higher expression of oncogenic CDX2 in some of the colon cancer types is due to loss of FBW7‐mediated CDX2 protein turn over." (PMID 29460395, 2018). "Additionally, we shed light on the morphological diversity within colon tumors, uncovering varying differentiation grades within the same tumor, reflecting the variations in CDX2 expression as well as the genetic complexity underlying these tumors." (PMID 38786321, 2024). "However, it should be noted that while our earlier studies show a link between Cdx2 loss and colon cancer development in general, the proximal vs. distal colon dependencies have remained unexplored." (PMID 38360902, 2024). "Our analysis further indicates that Category 1 of CDX2 expression, characterized by positive and moderate nuclear staining, is predominantly associated with well-differentiated (G1) and moderately differentiated (G2) colon tumors." (PMID 38786321, 2024). "Furthermore, the transcriptional program induced by Cdx2 loss specifically in proximal organoids was recapitulated in human proximal colon cancer samples from the Cancer Genome Atlas." (PMID 38360902, 2024). "A recent study also found that biomarkers could identify patients at very high risk of recurrence of colon cancer, such as CDX2 expression, which could be taken into consideration for decision-making." (PMID 34380513, 2021). "Furthermore, colon cancers that lack detectable CDX2 expression are associated with advanced disease stage, poor differentiation, vascular invasion, BRAF mutations, and the CpG island methylator phenotype." (PMID 33319153, 2020). "Furthermore, activation of Ras oncogene was associated with down regulation of the cdx-2 in colon cancer cells." (PMID 22824143, 2012). "Conversely, loss of Cdx2 in the colon causes metaplasia-like alterations, in which epithelia are misallocated towards an identity characteristic of more anterior structures, and this has provided important insights into understanding the progression of human serrated-type colonic tumors." (PMID 31739541, 2019). "The purpose of this study is to determine the role of ferroptosis in CDX2-mediated colon cancer chemical resistance." (PMID 41820294, 2026). "Our study uncovered a novel molecular mechanism by which CDX2 imparts ferroptosis resistance to colon cancer." (PMID 41820294, 2026). "Our study uncovered a novel molecular mechanism by which CDX2 confers ferroptosis resistance in colon cancer." (PMID 41820294, 2026). "The current study demonstrated a positive correlation between CDX2 expression and chemical resistance in colon cancer." (PMID 41820294, 2026). "In colonic tumor organoids derived from cis-Apc+/−Cdx1+/− and Cdx2+/−-cis-Apc+/−Cdx1+/− mice, the expression of Cdx1 and Cdx2 was lower than that in Apc+/− tumor organoids, whereas that of Lgr5 was higher." (PMID 40399276, 2025). "Through two phosphodegron motifs found within CDX2, FBXW7 promotes CDX2 ubiquitination and degradation in a GSK3β-dependent manner, resulting in decreased CDX2 expression and activity in colon cancer cells." (PMID 41373479, 2025). "We analyzed the gene expression profiles after expressing mouse wt-Cdx1 or wt-Cdx2 in human colon cancer-derived DLD1-TetOff cells." (PMID 40399276, 2025). "Upon examining the 43 colon tumors included in this study, we observed three recurrent patterns of diverse CDX2 nuclear expression intensity." (PMID 38786321, 2024). "Human colon cancers driven by BRAF mutation, predominantly occurring in the proximal colon, tend to occur in the context of CDX2 downregulation by epigenetic silencing." (PMID 38360902, 2024). "We identify that the homeobox transcription factor, CDX2, which is silenced by DNA methylation in proximal colon cancers, is a key mediator of the differential transcriptional programs." (PMID 38360902, 2024).
colon carcinoma (continued). "To this end, we conducted an immunohistochemical evaluation of CDX2 expression in 43 colon cancer cases to assess its prognostic capabilities further." (PMID 38786321, 2024). "These insights enhance our comprehension of CDX2’s role in colon cancer and support its integration into routine prognostic assessments as a dependable biomarker." (PMID 38786321, 2024). "In contrast, non-CDX2-suppressed colon cancers were most commonly of the CMS2 (33.8%) and CMS3 (23.7%) sub-types, less frequently (18.3%) of the CMS4 sub-type, and rarely belonged to CMS1." (PMID 39452477, 2024). "We thus tested if the transcriptional programs identified in the mouse proximal organoids lacking Cdx2 relates to the transcriptional state in human proximal colon cancers with low CDX2 expression." (PMID 38360902, 2024). "Further investigation is required to study how BRAFV600E regulates Cdx2 expression in ETBF-induced colon tumors." (PMID 38893159, 2024). "The Sidra-LUMC AC-ICAM cohort contained a lower percentage of colon cancers with CDX2 suppression (6%, 21 of 348 cases) and a higher percentage of non-CDX2-suppressed cases (62.9%, 219 of 348 cases) than TCGA." (PMID 39452477, 2024). "This comprehensive approach allows us to better understand the intricate role of CDX2 in colon cancer differentiation." (PMID 38786321, 2024). "In conclusion, our study has introduced a refined immunohistochemical scoring system for CDX2 expression that considers the inherent heterogeneity of colon tumors—a detail often missed by conventional immunohistochemical scoring systems." (PMID 38786321, 2024). "It is possible that the expression of BRAFV600E in Min mice maintains the expression of Cdx2 in ETBF-induced colon tumors." (PMID 38893159, 2024). "IHC analyses in a set of proximal and distal colon cancers further show that CDX2 protein level is lower in proximal compared to distal colon cancers." (PMID 38360902, 2024). "Here, the authors show that proximal and distal colon stem cells have distinct transcriptional programs mediated by the transcription factor CDX2, with differential roles in colon cancers based on anatomical location." (PMID 38360902, 2024). "Our studies here using genetically engineered organoid models provide important insights into the mechanistic bases of Cdx2’s differential roles in proximal vs. distal colon cancer development." (PMID 38360902, 2024). "In stage III colon cancer, there was a statistically significant overall survival benefit with adjuvant chemotherapy in both high- and low-CDX2-expression tumours." (PMID 39201360, 2024). "Using the TCGA colon cancer gene expression cohort, we identified gene sets whose expression is correlated with CDX2 expression in proximal and distal colon cancers, and analyzed expression of these genes in our organoid model." (PMID 38360902, 2024). "This would not only bolster the clinical utility of CDX2 but also facilitate the development of new personalized therapeutic strategies for colon cancer patients." (PMID 38786321, 2024). "The compelling correlation identified between CDX2 expression and conventional histopathological parameters emphasizes the prognostic significance of the CDX2 biomarker in colon cancer." (PMID 38786321, 2024). "Exosomal miR-24-3p from cancer-associated fibroblasts enhances methotrexate resistance and inhibits the apoptosis of colon cancer cells by suppressing caudal type homeobox 2 (CDX2) or hephaestin (HEPH) expression." (PMID 36612314, 2023). "Only one study reported that downregulating the transcription of caudal-type homeobox 2 (a tumor suppressor) resulted in a decrease in the transcription level of Fut2, thereby contributing to colon cancer cells metastasis." (PMID 36739428, 2023). "We also identified genes that are expressed at higher levels in colon cancer relative to the normal colon, such as CDX2." (PMID 37627195, 2023).
colon carcinoma (continued). "By overexpressing CDX2 using an hTERT (hypoxia-inducible human telomerase reverse transcriptase) promoter-driven plasmid, colon cancer cells were prevented from progressing malignantly (Al-Duhaidahawi., 2023)." (PMID 37719843, 2023). "Overexpression of CDX2 using a hypoxia-inducible human telomerase reverse transcriptase (hTERT) promoter-driven vector suppressed malignant progression of colon cancer cells both in vivo and in vitro." (PMID 35055034, 2022). "Colon tumors that lack CDX2 expression are more prone to have aggressive characteristics such as advanced stage, poor differentiation, vascularization, BRAF gene mutation, and the CpG island methylator profile." (PMID 35721501, 2022). "Homeobox protein CDX2 (CDX2) is a marker of differentiation of colon cancer cells and has been proposed as a strong prognostic marker in patients with colon cancer." (PMID 35027037, 2022). "Knockdown of CDX2 promoted colon cancer cell invasion in vitro and facilitated liver metastasis in vivo with inducing EMT phenotypes." (PMID 33239678, 2021). "Next, western blotting assay was performed to investigate differences in the expression levels of CDX2 in five colon cancer cell lines: RKO, Caco-2, HT-29, SW480 and Lovo." (PMID 33239678, 2021). "Analyses from TCGA databases also supported an inverse correlation between CDX2 and OS in the patients with colon cancer." (PMID 33239678, 2021). "While homeobox B7 (HOX B7) enhanced NHEJ efficiency in epithelial cells, caudal type homeobox 2 (CDX2) and thymocyte selection‐associated high‐mobility group box protein (TOX) inhibited the repair of broken ends in colon cancer and leukaemia." (PMID 33511782, 2021). "Subsequently, we demonstrated that CDX2 inhibited colon cancer cell invasion and migration in vitro." (PMID 33239678, 2021). "In agreement with the role of ECM in colon carcinoma progression, type I collagen has been shown to promote tumorigenesis by downregulating Cdx2 expression." (PMID 32426274, 2020). "CDX2 has been reported to be downregulated in colon cancer cells in the invasive front of the tumour." (PMID 32408894, 2020). "The results show that CDX2 expression is a prognostic and predictive biomarker of early‐stage colon cancer." (PMID 33319153, 2020). "Overexpression of CDX2 in colon cancer cell lines has shown decreased mobility and dissemination of cancer cells, further implicating fluctuation of CDX2 expression in the metastatic process." (PMID 32408894, 2020). "Previous studies have shown that Mex3a regulates CDX2 in human colon cancer and promoted proliferation in gastric cancer and glioblastoma." (PMID 32792503, 2020). "We found that the adhesion of colon cancer cells was significantly increased in postoperative versus preoperative serum, and that CDX2 expression affected the adhesive ability of cancer cells." (PMID 32408894, 2020). "In other CDX2 positive colon cancer cell lines, CDX2 acts as a linage survival gene that cannot be inactivated." (PMID 32408894, 2020). "In contrast, a direct involvement of CDX2 in the regulation of FUT2, which revealed potential binding sites for CDX1 and CDX2 and is involved in the generation of LeY/B antigens, was shown in colon cancer cell lines HT29 and DLD-1." (PMID 30909444, 2019). "Our study demonstrated that CDX2 inhibits colon cancer cell proliferation by delaying the transition from G0/G1 to S phase." (PMID 30631044, 2019). "A possible role for Cdx2 in colon cancer was initially suggested based on the knockout phenotype in mice; heterozygous mice had numerous tumors, although they never spontaneously advanced to carcinoma." (PMID 31739541, 2019). "In conclusion, these results indicated that CDX2 inhibits the proliferation and tumor formation of colon cancer cells by suppressing Wnt/β-catenin signaling." (PMID 30631044, 2019).
colon carcinoma (continued). "We find that a molecular sub-cluster of colon cancer cells with low CDX2 and VDR expression is specifically sensitive to chemotherapy, BRAF inhibitors and PI3K-mTOR inhibitors treatment." (PMID 31596728, 2019). "The precise molecular mechanism involved in the CDX2-mediated inhibition of colon cancer cell proliferation was investigated in our study." (PMID 30631044, 2019). "In this study, CDX2 knockdown in colon cancer cells promoted cell proliferation in vitro, accelerated tumor formation in vivo, and induced a cell cycle transition from G0/G1 to S phase, whereas CDX2 overexpression inhibited cell proliferation." (PMID 30631044, 2019). "In the present study, the TOP/FOP-Flash reporter assay showed that CDX2 knockdown or CDX2 overexpression led to enhanced or attenuated Wnt signaling activity in colon cancer cells." (PMID 30631044, 2019). "Our study reveals that CDX2 inhibits the proliferation of colon cancer cells by suppressing Wnt signaling activity." (PMID 30631044, 2019). "Our previous study revealed that in colon cancer cells, overexpression of CDX2 significantly inhibited cell viability and xenograft tumor formation." (PMID 30631044, 2019). "Western blot assay showed that downstream targets of Wnt signaling, including β-catenin, cyclin D1 and c-myc, were up-regulated or down-regulated in CDX2-knockdown or CDX2-overexpressing colon cancer cells." (PMID 30631044, 2019). "CDX2 knockdown in colon cancer cells led to a decreased percentage of cells in the G0/G1 phase and an increased percentage in the S phase compared to the control (all P < 0.05)." (PMID 30631044, 2019). "Other work in DLD-1 colon cancer cells shows that Oct1 rapidly changes transcriptional cofactors in response to MAPK signals at the target gene Cdx2." (PMID 31059499, 2019). "Overall, our results showed a molecular sub-cluster of colon cancer cells with low CDX2 and VDR expression was sensitive to chemotherapy, BRAF inhibitors and PI3K-mTOR inhibitors treatment." (PMID 31596728, 2019). "Conversely, CDX2 overexpression in colon cancer cells decreased the proportion of cells in the S phase and increased the proportion in the G0/G1 phase (all P < 0.05)." (PMID 30631044, 2019). "The precise molecular mechanisms by which CDX2 suppresses the Wnt signaling activity in colon cancer cells were further elucidated." (PMID 30631044, 2019). "Our previous study indicated that restoration of CDX2 expression markedly suppressed the aggressive phenotype of colon cancer cells, including viability, colony formation, and invasive and migratory abilities." (PMID 30631044, 2019). "Spearman correlation demonstrated a positive correlation between VDR and CDX2 expression in three published GEO expression datasets derived from primary colon cancer patients." (PMID 31596728, 2019). "The aim of the present study was to validate the prognostic impact of CDX2 in patients with stage II colon cancer." (PMID 30425348, 2018). "The expression of biomarkers CK20 and CDX2 for colon cancer were determined by immunocytochemistry assay." (PMID 30214379, 2018). "In conclusion, decreased expression of CDX2 is related to an inferior prognosis in stage II colon cancer." (PMID 30425348, 2018). "This retrospective study provides validation regarding the prognostic impact of CDX2 in patients with stage II colon cancer." (PMID 30425348, 2018). "The present results from two population-based cohorts of stage II colon cancer patients confirm reduced expression of CDX2 to be related to a poor prognosis." (PMID 30425348, 2018). "The results from the current study on two large, nationwide population-based cohorts, unbiased regarding sampling and treatment, and addressing patients with stage II colon cancer only, confirm a prognostic impact of CDX2." (PMID 30425348, 2018). "In yet another study they Identified CDX2, a master regulator of colon cell differentiation as a substrate of Fbw7 in colon cancer." (PMID 29460395, 2018).
colon carcinoma (continued). "In the present study we aimed to address this challenge by analysing the prognostic impact of CDX2 in two independent and unbiased, population-based cohorts of patients operated for stage II colon cancer." (PMID 30425348, 2018). "In human colon cancer cells, CDX2 limited cell proliferation and the Wnt/β-catenin signaling pathway by binding β-catenin and disrupting the β-catenin-TCF complex." (PMID 29156556, 2017). "In adult human, CDX2 expression is confined to the small intestine and colon, and in colon cancer it has been proposed as a tumor suppressor gene." (PMID 27902469, 2017). "Collectively, CDX2 inhibits the proliferation of cancer cells, including HT-29 colon carcinoma cells, Caco2 cells, and BGC823 gastric cancer cells." (PMID 27121315, 2016). "The results of a previous study showed that CDX2 overexpression in the colon cancer cell line SW480 improved the Claudin-1 gene promoter activity by 6-fold but only prompted a 4-fold increase in HCT116 cells." (PMID 27121315, 2016). "For example, CDX2, one caudal-related homeobox transcription factor, mediates E-selectin ligand expression in colon cancer cells with MYC together." (PMID 26083494, 2015). "An in vitro experiment showed that the CDX2 gene is associated with the increase in sLex/a expression and suppression of FUT2 in colon cancer cells during EGF/bFGF-induced epithelial–mesenchymal transition (EMT)." (PMID 24941225, 2014). "Here, we identify a novel CDX2 transcript (CDX2/AS) resulting from alternative splicing that is expressed concomitantly with wild type CDX2 in normal colonic epithelial cells, colonic tumors, and colon cancer-derived cell lines." (PMID 25101906, 2014). "Using an antibody recognizing the common amino-terminal activation domain, proteins at 42 kD (CDX2) and 38 kD (CDX2/AS) were identified in whole cell lysates from human colonic tumors, normal adjacent colonic mucosa, and several colon cancer cell lines." (PMID 25101906, 2014). "One possibility among many others is that in most of the previous studies CDX2 expression in pancreas (including PDAC) was compared to that in colon (including colon cancer)." (PMID 24489794, 2014). "Paradoxically, in other studies, CDX2 increases expression of pro-proliferative genes, increases anchorage-independent growth, undergoes overexpression in colonic tumors, and even functions as a lineage-survival oncogene." (PMID 25101906, 2014). "Baicalein, but not its glucuronidated metabolite baicalin, activates PXR in a Cdx2-dependent manner in vitro, in human colon carcinoma LS174T cells, and in the murine colon in vivo." (PMID 22815676, 2012). "Expression of Reg IV and CDX2 was analyzed by Western blot and quantitative reverse transcription–polymerase chain reaction in 9 GC cell lines and 2 colon cancer cell lines." (PMID 23133598, 2012). "Because we showed activation of LI-cadherin expression by CDX2 in the HT-29 colon cancer cell line, induction of Reg IV expression was investigated in the same cell line." (PMID 23133598, 2012). "Further, Cdx2-overexpression in colon cancer cells induces anchorage-independent growth and cell survival." (PMID 22719836, 2012). "In fact, Reg IV expression can be induced by CDX2 in cell lines derived from colon cancer in the present study." (PMID 23133598, 2012). "Our data regarding the importance of C-terminus in Cdx2-dependent transcriptional regulation is well supported by a previous study where deletion of the Cdx2 C-terminus (Cdx2CD) also reduced sucrase isomaltase reporter activity by ∼50% in colon cancer cells." (PMID 22719836, 2012). "Our data supporting a significant and parallel correlation between claudin-1 and Cdx2 expression in colon cancer patient samples highlights the importance of this regulatory relationship in the regulation of colonic homeostasis." (PMID 22719836, 2012).